FKBP4 (FKBP prolyl isomerase 4)
Description:
Immunophilin protein with PPIase and co-chaperone activities. Component of steroid receptors heterocomplexes through interaction with heat-shock protein 90 (HSP90). May play a role in the intracellular trafficking of heterooligomeric forms of steroid hormone receptors between cytoplasm and nuclear compartments. The isomerase activity controls neuronal growth cones via regulation of TRPC1 channel opening. Also acts as a regulator of microtubule dynamics by inhibiting MAPT/TAU ability to promote microtubule assembly. May have a protective role against oxidative stress in mitochondria.
Synonyms: FKBP51; HBI; FKBP52; FKBP59; Hsp56; PPIase; p52
Tractability: Small molecule: a structure with a bound ligand is known; a high-quality ligand is known; it has a binding pocket of medium quality; it belongs to a druggable protein family. PROTAC: UniProt records ubiquitination sites on it; ubiquitination databases record sites on it; its protein half-life has been measured; a small molecule that binds it is known.
Target class: Isomerase; Enzyme
Gene: Protein-coding gene on chromosome 12 (2,794,290 to 2,805,423, forward strand). Ensembl gene ENSG00000004478.
Subcellular location: Cytoplasm, cytosol; Mitochondrion; Nucleus; Cytoplasm, cytoskeleton; Cell projection, axon
Subcellular location (Human Protein Atlas): Cytosol; Nucleoplasm
Pathways (Reactome):
Cellular responses to stimuli: Attenuation phase; HSF1 activation; HSF1-dependent transactivation; HSP90 chaperone cycle for steroid hormone receptors (SHR) in the presence of ligand; Regulation of HSF1-mediated heat shock response
Signal Transduction: ESR-mediated signaling; Estrogen-dependent gene expression
Disease: Potential therapeutics for SARS
Gene Ontology:
Molecular function: heat shock protein binding; peptidyl-prolyl cis-trans isomerase activity; protein binding; RNA binding; FK506 binding; protein-macromolecule adaptor activity; ATP binding; GTP binding; nuclear glucocorticoid receptor binding; phosphoprotein binding
Biological process: protein folding; negative regulation of microtubule polymerization or depolymerization; negative regulation of neuron projection development
Cellular component: cytosol; extracellular exosome; mitochondrion; axonal growth cone; cytoplasm; nucleoplasm; axon; cytoskeleton; nucleus
Genetic constraint (gnomAD): Loss-of-function variants: 28 observed, 52.25 expected, observed/expected ratio (o/e) 0.54, 90% interval 0.4 to 0.74. The upper end of that interval is the gene's LOEUF score, 0.74, which puts it in group 3 of 6, group 1 being the genes least tolerant of losing a copy. Missense variants: 487 observed, 549.26 expected, observed/expected ratio (o/e) 0.89, 90% interval 0.82 to 0.96. Synonymous variants: 219 observed, 205.7 expected, observed/expected ratio (o/e) 1.06, 90% interval 0.95 to 1.19.
Homologues: Orthologues: chimpanzee FKBP4 (99% identical), macaque FKBP4 (98% identical), rabbit FKBP4 (90% identical), rat Fkbp4 (90% identical), mouse Fkbp4 (90% identical), pig FKBP4 (90% identical), guinea pig FKBP4 (89% identical), tropical clawed frog fkbp4 (62% identical), zebrafish fkbp4 (52% identical), Caenorhabditis elegans fkb-5 (11% identical), Caenorhabditis elegans fkb-4 (9% identical). Paralogues in human: FKBP5 (55% identical), FKBP15 (20% identical), FKBP10 (18% identical), FKBP8 (17% identical), FKBP9 (17% identical), FKBP6 (16% identical), FKBPL (13% identical), FKBP7 (12% identical), FKBP14 (11% identical), FKBP1A (11% identical), FKBP3 (11% identical), FKBP1C (10% identical), and 6 more.
Diseases named in the same sentence as FKBP4 in open-access papers:
FKBP4 is named in the same sentence as 96 diseases in open-access papers, as found by Europe PMC text mining. Sharing a sentence is not in itself a finding about the gene and the disease. The quoted sentences say what the papers report.
prostate carcinoma (22 papers, 2014 to 2025). A carcinoma that arises from epithelial cells of the prostate gland. "Depletion of either FKBP5 or FKBP4 in prostate cancer cells reduces AR dimer formation, chromatin binding, and phosphorylation, suggesting defective AR signalling." (PMID 41249932, 2025). "FKBP4 was found to be overexpressed in prostate cancer and hepatocellular carcinoma compared to control." (PMID 33936178, 2021). "The expression of FKBP4 was elevated in several cell lines of hormone-dependent cancers, including breast cancer cell lines and prostate cancer cell lines." (PMID 33354489, 2020). "A growing body of studies observed that FKBP4 expression was also upregulated in different types of cancers, e.g., head and neck cancer, prostate cancer, glioblastoma, ovarian cancer, colon cancer and so forth 3, 6, 18-22." (PMID 32194784, 2020). "For example, in prostate cancer FKBP4 is found to enhance the transcriptional activity of androgen receptor signaling." (PMID 32194784, 2020). "A significant increase (2.5-fold) in luciferase activity was observed in the prostate cancer cell line LNCaP, transfected with the FKBP4 promoter-luciferase vector compared to cells transfected with the empty reporter vector." (PMID 28852180, 2017). "FKBP4 expression is elevated in several cell lines of hormone-dependent cancers, including breast cancer cell lines 59, 60 and prostate cancer cell lines 61FKBP4 expression is elevated in several hormone-dependent cancer cell lines, including breast and prostate cancer cell lines." (PMID 38577594, 2024). "Furthermore, FKBP4 has multiple functions in various cancers, such as lung and prostate cancers, and glioblastoma." (PMID 39453509, 2024). "In addition, we explored therapeutic targets by investigating FOXA1 interacting protein within proteins encoded by upregulated genes in FOXA1 mutant prostate cancer, and identified six genes—HSP90AB1, KDM1A, FKBP4, H2BC15, WNT7B, and GRB7." (PMID 37958805, 2023). "Furthermore, FKBP4 was reported to be related to breast cancer, colorectal cancer, prostate cancer, and lung cancer." (PMID 36675710, 2022). "Thus, FKBP4 has been recognized to play a critical role in several hormone-dependent cancers, including breast and prostate cancer." (PMID 34112753, 2021). "To address this issue, we evaluated whether silencing c-Myc would have direct effects on the expression of FKBP4 in prostate cancer cells." (PMID 28852180, 2017). "Consistent upregulation of FKBP4 in prostate cancer was also shown in other studies." (PMID 28852180, 2017). "Finally, heat map analysis showed that prostate cancer and BPH tissues may be distinguished on the basis of the expression of the genes such as FKBP4, FGF8, c-Myc in addition to cyclinD1, CDK4, Ki-67 and p21." (PMID 28852180, 2017). "However, till date, to the best of our knowledge, there is no report of the role of a probable Myc-FKBP4 axis in prostate cancer." (PMID 28852180, 2017).
breast carcinoma (18 papers, 2011 to 2025). "Experimental design: In this study, we examined how loss of FKBP4 affect breast cancer progression and exploited protein interactomics to gain mechanistic insight into this process." (PMID 31660083, 2019). "Here we demonstrate for the first time that FKBP4 is associated with breast cancer progression and prognosis, especially of ER-negative breast cancer." (PMID 31660083, 2019). "A moderate-to-high FKBP4 expression was detected in the majority of grade 2 (82.8%) or grade 3 (85.7%) tumors, compared to grade 1 (46.7%), demonstrating that FKBP4 is associated with faster growing, moderately or poorly differentiated grade breast cancer, and an aggressive phenotype." (PMID 31660083, 2019). "Based on these results, we hypothesize that high expression of FKBP4 is associated with breast cancer progression, and more particularly, that FKBP4 might be a biomarker of poor prognosis in patient with ER/PR-negative breast tumor." (PMID 31660083, 2019). "FKBP4 expression was also found to be upregulated in breast cancer, in NSCLC by activating the Akt-mammalian target of rapamycin (mTOR) signaling pathway, and in colorectal cancer in males." (PMID 36675710, 2022). "A high level of FKBP4 was demonstrated in several human cancers, including breast cancer, ovarian cancer and osteosarcoma, using proteomic techniques." (PMID 36517562, 2022). "In this study, we firstly identified that FKBP4/NR3C1 axis was a novel negative regulator of NRF2 in human breast cancer (BC) cells." (PMID 35087512, 2021). "We further probed into genetic alterations and clinical outcomes of high and low level of FKBP4 expression in breast cancer patients." (PMID 32194784, 2020). "Recent studies illustrated that the expression of FKBP4 is related to breast cancer progression and prognosis." (PMID 33354489, 2020). "Previous studies have found that FKBP4 can interact with PI3K in breast cancer and activate Akt through PDK1 and mTORC2, thereby activating the Akt/mTOR signaling pathway." (PMID 33354489, 2020). "To evaluate the differential expression of FKBP4 in breast tissues, we used IHC to compare its expression in breast cancer and surrounding normal breast tissues." (PMID 31660083, 2019). "In the present study, we characterized the expression levels, the clinical correlations, and new role of FKBP4 in pathogenesis of breast cancers." (PMID 31660083, 2019). "In a previous study, our group showed that FKBP4 (alias FKBP52), an HSP90-associated co-chaperone, is a tumor-specific antigen capable of eliciting an immune response in breast cancer." (PMID 31660083, 2019). "To explore the mechanism of FKBP4 in breast cancer, we identified the FKBP4 proximal proteins using the recent BioID technique." (PMID 31660083, 2019). "As previously reported in breast cancer cell lines, we confirmed that FKBP4 expression was significantly higher in ER-positive tissues than in ER-negative tissues." (PMID 31660083, 2019). "We previously showed that FKBP4, an HSP90-associated co-chaperone, can elicit immune response as a tumor-specific antigen, and are overexpressed in breast cancer." (PMID 31660083, 2019). "And FKBP4 expression is upregulated in most cancer types such as breast cancer, squamous lung cancer, etc., which means the high expression of FKBP4 may be closely related to tumorigenesis." (PMID 39963131, 2025). "In addition to what we have shown in the present study, FKBP4 was shown to facilitate breast cancer proliferation via activating the PI3K/AKT pathway." (PMID 35981890, 2022). "However, under the influence of estrogen, the mRNA and protein of FKBP4 were up-regulated in breast cancer cells." (PMID 33936178, 2021). "However, the relationship between abnormal expression of FKBP4 and clinical outcome in luminal A subtype breast cancer (LABC) patients remains to be elucidated." (PMID 32194784, 2020).
breast carcinoma (continued). "Based on the Oncomine database, we discovered that FKBP4 mRNA expression was significantly upregulated in cancerous samples compared with normal samples in more than nine types of cancer, including breast cancer, bladder cancer, colorectal cancer, gastric cancer, leukemia and so forth." (PMID 32194784, 2020). "Moreover, the expression of FKBP4 in breast cancer tissues and preinfiltration breast cancers was higher than that in normal breast tissues." (PMID 33354489, 2020). "Hence, these data suggested that FKBP4 has a strong impact on growth activity in breast cancer through an ER-independent mechanism, at least in these ER-negative models." (PMID 31660083, 2019). "Moreover, we and others have reported that FKBP4 was found up-regulated in breast cancer tissues and breast cancer cell lines, both at the mRNA and protein levels 17-19." (PMID 31660083, 2019). "However, the relationship between abnormal expression of FKBP4 and clinical outcome in luminal A subtype breast cancer (LABC) patients remains unknown." (PMID 32194784, 2020). "Altogether, these results suggest that FKBP4 may be a useful biological marker to estimate breast cancer progression and prognosis, and may functionally play a role in promoting breast cancer growth in ER-positive and more interestingly in ER/PR-negative tumors." (PMID 31660083, 2019). "We observed that inhibition of FKBP4 expression alters cell growth in a triple negative (ER-, PR-, and HER2-negative) breast cancer cell model and a murine xenograft tumor model." (PMID 31660083, 2019). "Interestingly, using standard IP-approach, we confirmed the interaction of FKBP4 with the catalytic subunit of PI3K, PIK3C2A, suggesting that the interaction between FKBP4 and PI3K could be central in the functional impact of FKBP4 in breast cancer cells." (PMID 31660083, 2019). "Same results on Akt phosphorylation were obtained with the 3 other human breast cancer cell lines (MCF-7, T47D, and MDA-MB-436), regardless of the single FKBP4 siRNAs used." (PMID 31660083, 2019).
endometriosis (15 papers, 2016 to 2024). The growth of functional endometrial tissue in anatomic sites outside the uterine body. "In humans, FKBP4 mRNA expression was decreased in the endometrium with endometriosis compared to controls." (PMID 37234872, 2023). "Following induction of endometriosis in baboons, the mean expression of miRNA-29c in the eutopic endometrium was increased with a coexisting decrease in FKBP4 level in this tissue." (PMID 33411206, 2021). "Compared with controls, FKBP4 mRNA expression was decreased in the endometrium of women with endometriosis." (PMID 33936178, 2021). "The upregulation of miR-29c, resulting in the decrease of FKBP4 during the window of implantation, could lead to progesterone resistance in women with endometriosis, promoting infertility." (PMID 38892003, 2024). "Studies have revealed that the overexpression of miR-29c in endometriosis could impair the progesterone response by diminishing the levels of FK506-binding protein 4/52 (FKBP4/52) genes." (PMID 37108154, 2023). "Furthermore, studies in a primate (baboon) model for endometriosis revealed that P4 resistance in endometriosis is modulated by the altered expression of miRNA-29c and changes in the levels of its target transcript, FK506-binding protein 4 (FKBP4)." (PMID 33411206, 2021). "The alteration of miR-29c resulting in the decrease of FKBP4 during the window of implantation could lead to the progesterone resistance in women with endometriosis, promoting infertility." (PMID 32183093, 2020). "FKBP4 may also be involved in the progesterone resistance process of endometriosis." (PMID 33354489, 2020). "This miRNA is upregulated in endometriosis, resulting in the decreased expression of one of its targets, the FK506-binding protein 4 (FKBP4) gene." (PMID 38892003, 2024). "This study revealed that miR-29c expression increased, while mRNA levels of its predicted target, FK506-binding protein 4 (FKBP4), decreased in eutopic endometrial tissue from baboons after the induction of experimental endometriosis." (PMID 35406659, 2022). "In a baboon model of endometriosis, miR-29c was also found to be upregulated, while the transcript levels of its target, FK506-binding protein 4 (FKBP4), decreased." (PMID 34638843, 2021). "This miRNA is upregulated in endometriosis decreasing the expression of one of its targets, FK506-binding protein 4 (FKBP4) gene." (PMID 32183093, 2020). "miR-29c, which is also overexpressed in the eutopic endometrium of women with endometriosis and baboon models, could downregulate PGR by decreasing FK506-binding protein 4 (FKBP4) levels." (PMID 37108154, 2023).
Alzheimer disease (11 papers, 2010 to 2024). A progressive, neurodegenerative disease characterized by loss of function and death of nerve cells in several areas of the brain leading to loss of cognitive function such as memory and language. "Additional FKBPs have been put forward as potential drug targets in steroid hormone-associated cancer and psychotic disorders (FKBP4, 5, 8), and Alzheimer’s disease (FKBP1A, 4, 5)." (PMID 35456020, 2022). "Patients with Alzheimer's disease have abnormally reduced levels of FKBP4 in the brain and can cause the formation of nerve fiber tangles." (PMID 33354489, 2020).
lung carcinoma (9 papers, 2020 to 2025). "At the same time, the FKBP4 expression was also analyzed using TCGA Lung Cancer database and discovered that the expression of the FKBP4 gene was upregulated in lung adenocarcinoma compared to that in normal tissue." (PMID 33354489, 2020). "Because the high FKBP4 level is known to promote migration and invasion of lung cancer cell, we thus wondered whether it plays a similar role in COAD cells." (PMID 35981890, 2022). "The SHC1, FKBP4, NRAS, and KRAS had higher expressions in lung cancer tissues compared with lung normal tissues in LUAD." (PMID 33936178, 2021). "The direct relationship between estrogen and FKBP4 in lung cancer has not been fully elucidated." (PMID 33936178, 2021). "FKBP4 did not co-precipitate HSP70 in HEK293T cells, unlike what was previously observed in lung cancer and bronchial epithelial cell lines." (PMID 41203126, 2025).
depression (6 papers, 2012 to 2023). "In addition, FKBP4, PKD2, CSGALNACT1, and VAMP2 have been reported in relation to depression (or mood disorders)." (PMID 26728011, 2016).
colorectal cancer (5 papers, 2020 to 2025). A primary or metastatic malignant neoplasm that affects the colon or rectum. "Given that TALIN-1, MRE11, and CCT8 interact with E-cadherin, that FASN, FLNA, and DDX3X are implicated in EMT, and that FKBP4 expression is upregulated in colon cancers, we examined E-cadherin expression in human colorectal carcinoma HCT116 cells under the FKBP4 knockdown." (PMID 41203126, 2025). "Additionally, KDM5D inhibited tumor growth in colorectal cancer by demethylating E2F1 and suppressing FKBP4 transcription, thereby suggesting that it could possibly serve in the management of colorectal cancer in males." (PMID 37218871, 2023).
hepatocellular carcinoma (4 papers, 2019 to 2021). A malignant tumor that arises from hepatocytes. "The upregulation of FKBP4 was also detected in hepatocellular carcinoma (HCC), which was strongly related to HCC staging." (PMID 34112753, 2021). "Similar observations were reported in prostate biopsy tissues 45 and hepatocellular carcinoma 46, where FKBP4 was proposed to be a tumor biomarker." (PMID 31660083, 2019).